EGFR (epidermal growth factor receptor)
Diseases named in the same sentence as EGFR in open-access papers (continued):
Sharing a sentence is not in itself a finding about the gene and the disease.
lung adenocarcinoma (continued). "We observe human lung adenocarcinomas without copy number loss of DOK2, and expression of mutated EGFR induces tumor formation in Dok2 wild-type mice, albeit more slowly and less effectively than in a Dok2 null genetic context." (PMID 24255704, 2013). "Screening the 35% of never smokers with adenocarcinoma of the lung who will be both EGFR and KRAS wild type should, therefore, capture 92% of the ALK rearrangements contained within the never smoking adenocarcinoma population." (PMID 22374459, 2012). "This leads to consider the need for studies that enhance the molecular changes that, like EGFR, K-ras and ALK genes for lung adenocarcinoma, at prognostic and/or predictive levels may give chances for an effective therapeutic response in these patients." (PMID 23236352, 2012). "The interphase in situ hybridization technique is becoming a routinely available standard molecular assessment requested to reference Pathology Labs, due i.e. to the value of the Her-2 gene in breast, gastric cancers, 1p/19q in oligodendrogliomas or EGFR and ALK genes in lung adenocarcinoma." (PMID 23236352, 2012). "EGFR-TKIs sometimes cause drastic tumor regression in specific subgroups of patients with advanced NSCLC, including women, non-smokers, patients with lung adenocarcinoma (ADC) histology, patients of Asian origin and patients with EGFR mutations." (PMID 21791074, 2011). "As a result, ECOG PS 2–4 (Hazard ratio (HR): 5.52, 95% confidence interval (CI): 2.04–14.95; p = 0.001) and positive staining of EGFR IHC (HR: 0.29, 95% CI: 0.12–0.68; p = 0.004) were the independent factors that significantly affected PFS for the lung adenocarcinoma patients treated with EGFR TKIs." (PMID 21858063, 2011). "Basically, mutations involving EGFR, ERBB2 and KRAS are mutually exclusive and are thought to represent early events in the carcinogenesis of lung adenocarcinoma in never (EGFR and ERBB2) and current smokers (KRAS)." (PMID 21532835, 2010). "Although direct evidence regarding the interaction between SOX9 and the EGFR/KRAS pathways in lung adenocarcinoma remains limited, studies in other types of cancer suggest that SOX9 may regulate the biological behavior of lung adenocarcinoma cells through crosstalk with these signaling pathways." (PMID 41268614, 2026). "Notably, some lung SCC samples exhibited mutations typically associated with lung adenocarcinoma or other non-squamous histology, such as KRAS, EGFR, and MET mutations." (PMID 41515905, 2025). "Compared to EGFR mutations, which are more commonly observed in elderly patients, ALK rearrangements are predominantly found in younger patients (<60 years old), non-smokers, or light smokers with lung adenocarcinoma." (PMID 41020204, 2025). "However, the metabolic mechanisms that drive ferroptosis resistance in lung adenocarcinoma (LUAD), particularly in the context of EGFR-TKI tolerance, remain unclear." (PMID 41293164, 2025). "Notably, co-mutations in EGFR and PIK3CA could reflect crosstalk between the EGFR and PI3K-AKT-mTOR pathways, potentially indicating poor prognosis in advanced EGFR-mutant lung adenocarcinomas." (PMID 40502411, 2025). "However, the differences in the tumor microenvironment signature between EGFR-mutant lung adenocarcinoma patients with high and low TLS expression are still not fully clear." (PMID 40723259, 2025). "To study whether PPP3CB Ex16 accumulation occurs at disease progression under EGFR TKI treatment, we took advantage of a retrospective cohort of 43 EGFR-mutant lung adenocarcinoma patients with paired tissue sections (pre- and post-progression after EGFR TKI treatment)." (PMID 39353739, 2024). "In addition, 126 ALK‐positive and 161 EGFR‐positive lung adenocarcinoma patients, excluding nonadenocarcinoma patients, were also analyzed." (PMID 38400801, 2024).
lung adenocarcinoma (continued). "By focusing on EGFR/ALK wild‐type patients, we aimed to elucidate molecular mechanisms and potential biomarkers related to PD‐L1 expression and the response to immunotherapy within this specific and clinically significant subgroup of lung adenocarcinoma patients." (PMID 38396367, 2024). "When RFS was compared according to EGFR status, we found a significant difference in RFS between PD-L1-positive and PD-L1-negative cases in patients with EGFR-mutated lung adenocarcinoma (log-rank, p=0.006), but not in patients with EGFR wild-type lung adenocarcinoma (log-rank, p=0.646)." (PMID 39281386, 2024). "However, another real‐world study reported that denosumab had no significant prognostic effects in lung adenocarcinoma patients with BoM treated with first‐line EGFR–TKIs." (PMID 38549499, 2024). "Additionally, this could be indirect evidence for the connection of the EGFR pathway with AQP5 expression and its influence on the invasive potential of lung adenocarcinoma." (PMID 36766810, 2023). "Since almost all the EGFR-mutant NSCLCs were lung adenocarcinoma (more than 95% in ADAURA trial), EGFR TKI, instead of sequential chemoradiotherapy, was currently the standard of treatment for stage IIIA-N2 EGFR-mutant lung adenocarcinoma after complete resection." (PMID 37188197, 2023). "In the absence of diagnosis of lung adenocarcinoma and target testing to determine whether EGFR was positive, oral erlotinib treatment was received." (PMID 37276214, 2023). "Some clinical trials draw a conclusion that upfront brain RT based on first-line EGFR-TKIs might improve intra-cranial PFS but not OS in EGFR-mutant lung adenocarcinoma patients with BMs." (PMID 37759881, 2023). "In the exploration of the correlation between MMP11 and immune response, we found that MMP11 expression in lung adenocarcinoma did not correlate with cytotoxic T-cell level and the clinical benefit of ICB therapy regardless of whether EGFR is mutated or not." (PMID 36756152, 2023). "However, to the best of our knowledge, there have been no studies on the mechanism of acquired EGFR-TKI resistance in relation to ANGPTL4 in lung adenocarcinoma cells, and it remains unknown whether ANGPTL4 is involved in EGFR-TKI resistance." (PMID 36467503, 2022). "Our design provides an alternative method to non-invasively assess EGFR information and to assist in decision-making when applying TKI as an initial treatment in inoperable or inappropriate situations for surgical treatment of lung adenocarcinoma manifesting as pGGN." (PMID 36119545, 2022). "Moreover, LOC389641 may activate STAT3 signalling by increasing the expression of EGFR and MET and therefore downregulate cleaved-PARP to inhibit cell apoptosis in lung adenocarcinoma." (PMID 35379783, 2022). "Also, because the SNPs of other gene would interact with EGFR genotype and affect the characters of lung adenocarcinoma, a similar action may occur between GAS5 SNPs and EGFR which need additional evaluation." (PMID 36011604, 2022). "Anti-angiogenic therapy may be a possible strategy for the EGFR-negative lung adenocarcinoma population." (PMID 35860549, 2022). "Moreover, the GAS5 SNP rs55829688 TC+CC did not alter all the clinical manifestations of lung adenocarcinoma with all types of the EGFR genotype." (PMID 36011604, 2022). "In the subgroup analyses of EGFR wild type, the GAS5 SNP rs145204276 Ins/Del + Del/Del are related the tumor stage and distal metastases of lung adenocarcinoma in the non-smoker population and enhance the lymph node invasion of lung adenocarcinoma in the ever-smoker group." (PMID 36011604, 2022).
lung adenocarcinoma (continued). "Consistent with the results of basic experiments with HPV oncoproteins enhancing EGFR nuclear translocation, we found a strong correlation between HPV 16E6/18E6 expression and nEGFR/mEGFR expression in NSCLC tissues with a preference in early-stage lung adenocarcinoma." (PMID 36358752, 2022). "However, the issue regarding the secondary resistance to EGFR-TKIs in lung adenocarcinoma patients has still not been adequately addressed." (PMID 36467503, 2022). "Consequently, the genotypes of these two genetic factors, the EGFR and GAS5, may interact and alter the clinical course of lung adenocarcinoma." (PMID 36011604, 2022). "Finally, the in vitro experiments showed that SD could block the EGFR/JAK/STAT and EGFR/PI3K/AKT signaling pathways to different degrees to inhibit the proliferation of lung adenocarcinoma A549 cells and increase apoptosis." (PMID 35190747, 2022). "Therapeutic strategies, targeting EGFR, have greatly improved the progression-free survival (PFS) and overall survival (OS) of the patients with NSCLC, especially in the non-smoking females with lung adenocarcinoma and 80% EGFR mutation rate." (PMID 36153486, 2022). "However, the predictive value of the L-signature was not validated in lung adenocarcinoma patients treated with EGFR inhibitors due to the lack of appropriate datasets." (PMID 35016696, 2022). "We also suggest that lung adenocarcinomas harbouring BCAR4 fusions might be a clinically relevant subgroup with a targetable oncogenic driver, among patients without EGFR and KRAS mutations." (PMID 33204025, 2021). "Moreover, DNAJB1/HDJ1 binds to mitogen-inducible gene-6 (MIG6), a tumor suppressor that inhibits the EGFR signaling, which decreases the protein level of MIG6 by enhancing its ubiquitination, leading to upregulation of the EGFR signaling pathway in A549 lung adenocarcinoma and HCT116 CRC cell lines." (PMID 34948322, 2021). "EGFR activation depended on EGF in the EGFR-nonaddictive lung adenocarcinoma." (PMID 34367939, 2021). "Two patients with lung adenocarcinoma were both EGFR negative, ALK negative and KRAS negative." (PMID 34717570, 2021). "Interestingly, the BCAR4 fusion-positive patients showed the consistent features of being never-smokers, exhibiting absent or rare mutations of EGFR or KRAS genes and diagnosis with lung adenocarcinoma." (PMID 33204025, 2021). "To determine whether the MET-induced EGFR inhibition observed in lung tumors from EGFR/MET mice was clinically relevant, we performed a correlation analysis of pEGFR and pMET expression in a TCGA cohort of patients with lung adenocarcinoma." (PMID 34298655, 2021). "In addition, activated EGFR reflected by the levels of phosphotyrosine 1068, 1086, and 1145 of EGFR had no impact on c-Src activation, while TKIs attenuated EGFR activation to induce cell deaths of lung adenocarcinoma." (PMID 34367939, 2021). "However, such high correlations between PD-L1 expression and the EGFR mutation status are not uniformly reported across the literature for NSCLC samples including both lung squamous cell carcinoma (SCC) and lung adenocarcinoma (LUAD)." (PMID 35052732, 2021). "Loss of Gene 33, both homozygous deletion and haploinsufficiency, accelerates the initiation and progression of lung adenocarcinoma driven by transgenic expression of mutant EGFRs (L858R or del-746-750) in mice, likely a result of increased MAPK activity due to reduced inhibition of EGFR." (PMID 34206547, 2021). "Patient 2: A 55-year-old female was diagnosed with left lung adenocarcinoma with intrapulmonary metastases and multiple bone metastases staged with T4N3M1 and received palliative comprehensive treatment based on target therapy of epidermal growth factor receptor (EGFR) inhibitor in April 2018." (PMID 33029098, 2020). "Although approximately 50% of lung adenocarcinoma were EGFR-derived in Asia, a significant number of patients have no or unknown gene-mutation." (PMID 31965001, 2020).
lung adenocarcinoma (continued). "Hence, these results suggest that cytoplasmic ERβ1 was responsible for EGFR TKI resistance slightly through non-genomic mechanism in EGFR mutant lung adenocarcinoma." (PMID 33585221, 2020). "Though the frequency of EGFR KDD may be underestimated due to the technical difficulty, it has only been reported in a limited number of entities since the initial description in 1998, with the reported highest frequency being 0.2% in lung adenocarcinoma." (PMID 32490123, 2020). "Further phase III trials, which compared the outcomes of first- or second-line EGFR-TKI treatments with those of platinum doublets, confirmed the beneficial effects of mEGFRs on the progression-free survival and response rates in patients with lung adenocarcinoma." (PMID 32517757, 2020). "Baseline demographics in EGFR positive and negative lung adenocarcinoma subjects." (PMID 32053675, 2020). "Pemetrexed/carboplatin plus anlotinib could be considered for the treatment of epidermal growth factor receptor wild-type, anaplastic lymphoma kinase-negative lung adenocarcinoma with BM." (PMID 32899099, 2020). "Nevertheless, the role of IMs in the progression of EGFR mutant lung adenocarcinoma remains undefined and is not known if the reduction of IMs could have an increased effect on tumor burden reduction compared to AMs." (PMID 32125091, 2020). "Among patients with EGFR mutant lung adenocarcinoma, afatinib use may not provide longer OS compared with first-generation TKIs." (PMID 33489886, 2020). "Here, we present this unique case of a Chinese woman who was confirmed as late stage lung adenocarcinoma with intraventricular metastases without parenchyma lesions and had a good response to target therapy with Epidermal Growth Factor Receptor- tyrosine kinase inhibitor (EGFR-TKI)." (PMID 32393286, 2020). "PC9 is a human lung adenocarcinoma cell line with EGFRL858R mutation without FGFR1 expression, while H520 is a human lung squamous cell carcinoma cell line with the high expression of FGFR1 but without EGFR expression." (PMID 31998131, 2019). "In the subset of patients with EGFR mutant lung adenocarcinoma, no significant survival difference was found between patients with tumors carrying exon 19 deletions and patients harboring exon 21 p.L858R point mutation (mOS 47.0 vs. 58.7 mo, HR 1.02, 95% CI 0.34–3.08, p = 0.977)." (PMID 31386689, 2019). "Since EGFR, BRAF, ERBB2, MET and the EML4-ALK translocation product are clients of HSP90, acting as oncodrivers in different clinico-pathological subsets of lung adenocarcinoma, degradation of these oncoproteins through HSP90 inhibition leads to loss of tumor-cell viability." (PMID 31370342, 2019). "The EGF receptor is expressed on the cell membrane and patients with lung adenocarcinoma can be classified as EGFR positive or EGFR negative, according to whether or not there is a mutation in the receptor." (PMID 30486412, 2018). "Furthermore, TCGA Research Network7 also indicated that there might be a correlation between EGFR and LOX mRNA expression in lung adenocarcinoma patients." (PMID 29472856, 2018). "However, the correlation between MMP-1 and EGFR-TKI–resistant lung adenocarcinoma has not been studied." (PMID 29463039, 2018). "Targeting EGFR protein has been reported to be an important treatment option for NSCLC; therefore, EGFR proteins might be an indicator for treatment responses in patients with lung adenocarcinoma." (PMID 29950164, 2018). "In addition, our model is unique as it can better represent human lung adenocarcinoma cases with no common KRAS and EGFR mutations." (PMID 29415661, 2018). "Notably, the two lung adenocarcinoma patients in our cohort that carried the highest number of oncogenic gene alterations, showed no clinical response to EGFR-TKI therapy." (PMID 29343775, 2018).
lung adenocarcinoma (continued). "Since LCSE reduced EGFR signaling, downregulated Erk-1/-2 and Akt, and arrested the G1 phase in A549 cells, our results indicated a possible novel role of LCSE in the control of lung adenocarcinoma cells in terms of cell-cycle progression from the G1 phase to the S phase." (PMID 28056952, 2017). "Moreover, the National Health Insurance Administration has been reimbursing advanced EGFR-mutant lung adenocarcinoma patients receiving EGFR-TKI as the first-line of treatment since 2011; hence, every EGFR-mutant patient in the present study had an equal chance to receive EGFR-targeted therapy." (PMID 29228697, 2017). "In this regard, EGFR mutated lung adenocarcinoma cell lines, HCC827 and HCC4006, contained a subpopulation of cells that have undergone epithelial-to-mesenchymal transition and survived independent of the activated EGFR." (PMID 30370422, 2016). "In conclusion, the mutation of EGFR was associated with adenocarcinoma, smoking status, and gender and the polymorphisms of the IGF1R rs2229765 gene were associated with the L858R mutation of EGFR in female lung adenocarcinoma patients who had never smoked." (PMID 27213344, 2016). "Results from the LUX-Lung 3 and LUX-Lung 6 trials showed a benefit in OS for patients with EGFR del19-positive lung adenocarcinoma with the use of afatinib, but the drug did not result in significant improvements in OS compared to conventional chemotherapy in patients with the L858R mutation." (PMID 27811976, 2016). "Our work suggests that GAS5 LncRNA expression may represent a valuable marker for diagnosis and outcome predictions in patients with lung adenocarcinoma and that increased GAS5 expression may overcome the resistance to EGFR-TKIs in resistant lung adenocarcinoma, both in vitro and in vivo." (PMID 25925741, 2015). "We extended study of epigenetic priming to a patient-derived xenograft (PDX) model of lung adenocarcinoma, LX7, which has poorly differentiated histology, is negative for KRAS, EGFR (exons 18–21), and BRAF mutations, and is negative for ALK-fusions by cytogenetic analysis." (PMID 25474141, 2015). "We report a case of a 54-year-old male with a seven-year survival after being diagnosed with Stage IV epidermal growth factor receptor (EGFR) mutation-negative and anaplastic lymphoma kinase (ALK) mutation-negative adenocarcinoma of the lung, demonstrating an exceptional response to treatment." (PMID 26835190, 2015). "Because mutations of EGFR, KRAS, HER2, BRAF, as well as ALK fusions have been well established to be existed in lung adenocarcinoma, these mutation and fusion genes that ‘drives’ lung adenocarcinoma were not screened in lung squamous cell carcinoma." (PMID 25198510, 2014). "Therefore, further targeting SOX2 in EGFR-mutant cancer with PI3K/AKT inhibitors in lung adenocarcinoma cell lines, may yield better results." (PMID 25114775, 2014). "Our results suggest that miR-19a, miR-19b, miR-195, miR-122 and miR-590-5p may predict the prognosis of lung adenocarcinoma with mutant type of EGFR in non-smoking females." (PMID 24282590, 2013). "In lung adenocarcinoma KRAS mutations are associated with poor prognosis and non-responsiveness to EGFR inhibitors whereas KRAS wild-type tumors with EGFR mutations are linked to better prognosis and response to EGFR inhibitors." (PMID 24280411, 2013). "Furthermore, a large gene set derived from microarrays well stratified lung adenocarcinomas in one ALK-mutated and two EGFR/KRAS/ALK-mutation negative subgroups." (PMID 27605195, 2013). "As not all the lung adenocarcinoma are sentitve to TKI, as only a few cell lines are sensitive to TKI, such as A549, PC9, HCC827, CALU-3, HCC4006 those harboring the acquired mutation in the EGFR gene." (PMID 23520479, 2013).